LOXL3 (lysyl oxidase like 3)
Diseases named in the same sentence as LOXL3 in open-access papers (continued):
Sharing a sentence is not in itself a finding about the gene and the disease.
melanoma (continued). "Complementary in vitro and in vivo studies in mouse melanoma cells confirmed Loxl3’s contribution to melanoma progression and metastasis, in part by modulating phenotypic switching through Snail1 and Prrx1 EMT-TFs." (PMID 35267510, 2022). "Macroscopically, proximal (subiliac) and distant (superficial parotid) lymph nodes were remarkably smaller and showed less pigmentation in mice bearing Loxl3 KO melanomas than in Loxl3 WT tumor animals 42 days upon 4-HT-induced development of melanomas." (PMID 35267510, 2022). "With the assistance of lentivirus, we constructed LOXL3‐downregulation and overexpression A375, SK‐MEL‐28 and A2058 melanoma cells (shLOXL3‐1, shLOXL3‐2 and OE LOXL3)." (PMID 36324258, 2022). "Given the relevance of LOXL3 in human melanoma, we generated a genetic mouse model to further understand the role of Loxl3 in melanoma formation and progression." (PMID 35267510, 2022). "LOXL3 overexpression in melanoma has been characterized, and some suggest its expression is a requirement for melanoma cell survival." (PMID 36230844, 2022). "The results presented here suggested that the LOXL3–SNAIL1–PRRX1 axis contributes to phenotypic switching in melanoma and supports tumor progression." (PMID 35267510, 2022). "In this context, deletion of Loxl3 in melanocytes resulted in increased melanoma latency, decreased tumor growth, and notable reduction of lymph node metastatic dissemination." (PMID 35267510, 2022). "Santamaria and colleagues reported that melanoma cells depend on the expression of lysyl oxidase-like 3 (LOXL3) for survival." (PMID 33800547, 2021). "This research also indicated that LOXL3 was necessary for completing proper mitosis and that the silencing of LOXL3 in melanoma cells triggered cancer cell apoptosis." (PMID 33058284, 2020). "In the cytoplasm, LOXL3 was observed at perinuclear localization in HeLa cells overexpressing LOXL3, in melanoma cells, and in Madin–Darby canine kidney cells." (PMID 31340433, 2019). "LOXL3 silencing promoted DNA damage response in melanoma cells, with accumulation of double-strand breaks, aberrant mitosis with accumulation of cells in the G2/M phase, and apoptosis." (PMID 31340433, 2019). "Considering LOXL3 mRNA expression levels and the cell lines corresponding to each tumor type analyzed (n = 61 for melanoma, n = 4 for chondrosarcoma) we further evaluated LOXL3 role in melanoma." (PMID 29229995, 2018). "All melanoma cell lines depleted for LOXL3 expression halt proliferation between 5–8 days post-infection (dpi) compared to control cells infected with a non-targeting control (NTC)." (PMID 29229995, 2018). "We, therefore, performed gain and loss-of-function experiments to determine the contribution of LOXL3 to melanoma pathogenesis." (PMID 29229995, 2018). "Accordingly, tumor growth is delayed in immunocompromised mice orthotopically injected with LOXL3-depleted melanoma cells corroborating LOXL3 involvement in melanomagenesis." (PMID 29229995, 2018). "Here, we found that also the expression of LOX, LOXL1, and LOXL3 encoding proteins that crosslink ECM proteins (collagens and elastin) are increased in many melanoma cells and primary melanomas." (PMID 30701028, 2018). "Our data uncover an unprecedented role for LOXL3 in melanoma biology and support the relevance of LOXL3 as a novel druggable target for therapeutic intervention in this severe disease." (PMID 29229995, 2018). "We show that LOXL3 silencing impairs cell proliferation and triggers apoptosis in various melanoma cell lines." (PMID 29229995, 2018). "To investigate LOXL3 involvement in melanoma, we initially evaluated the effects of LOXL3 silencing in a panel of human melanoma cells." (PMID 29229995, 2018). "To validate the interactions, we performed immunoprecipitation experiments in 501MEL and A375P melanoma cells expressing ectopic LOXL3 or LOXL3Δ FLAG-tagged proteins." (PMID 29229995, 2018).
melanoma (continued). "Our studies reveal that human melanoma cells are addicted to LOXL3 expression since LOXL3 knockdown halts cell proliferation and triggers apoptosis." (PMID 29229995, 2018). "Data mining from the TCGA showed that upregulated LOXL3 mRNA levels significantly correlate with a higher presence of copy number alterations (CNA) and overall mutations in human melanoma samples (n > 300 patients)." (PMID 29229995, 2018). "TCGA data interrogation revealed that LOXL3 promoter methylation levels (detected with four independent probes) negatively correlate with LOXL3 mRNA expression in melanoma tumors." (PMID 29229995, 2018). "Gain and loss-of-function studies have clarified LOXL3 involvement in melanoma and the consequences of LOXL3 deregulation in primary and metastatic melanoma cell lines." (PMID 29229995, 2018). "Upon LOXL3 depletion, melanoma cells display a faulty DNA damage response (DDR), characterized by ATM checkpoint activation and inefficient ATR activation leading to the accumulation of double-strand breaks (DSBs) and aberrant mitosis." (PMID 29229995, 2018). "Further supporting a pro-oncogenic role in melanoma, LOXL3 favors tumor growth in vivo and cooperates with oncogenic BRAF in melanocyte transformation." (PMID 29229995, 2018). "Accordingly, analysis of a large cohort of primary and metastatic melanoma cell lines confirmed increased LOXL3 expression at both LOXL3 mRNA and protein levels in melanoma cells compared to primary and immortalized human melanocytes." (PMID 29229995, 2018). "In silico expression analyses followed by experimental validation in a comprehensive cohort of human cell lines revealed a significant upregulation of LOXL3 in human melanoma." (PMID 29229995, 2018). "We also propose that LOXL3 roles in melanoma are mostly due to the intracellular protein, based on LOXL3 subcellular localization and its biologically relevant association to intracellular partners." (PMID 29229995, 2018). "Taken together, we conclude that human melanoma cell lines expressing LOXL3 are addicted to the maintenance of its expression." (PMID 29229995, 2018). "Upon LOXL3 silencing, melanoma cells fail to activate and execute a competent DDR required for cell survival." (PMID 29229995, 2018). "Both LOXL2 and LOXL3 are commonly expressed in melanoma cell lines." (PMID 41250755, 2025). "Furthermore, suppression of LOXL3 expression enhances DNA damage signals within melanoma cells, leading not only to an increase in DNA double-strand breaks (DSB) and defects in G2/M phase progression, but also to reduced cellular apoptosis." (PMID 41250755, 2025). "Research has demonstrated that LOXL3 plays a role in the initiation and progression of melanoma." (PMID 41250755, 2025). "In summary, both LOXL2 and LOXL3 are frequently overexpressed in melanoma." (PMID 41250755, 2025). "The association between the overexpression of LOXL3 and the transformation of immortalized human melanocytes carrying the BRAF V600E mutation into malignant cells was originally described in an in vitro experiment on melanoma cell lines." (PMID 39273022, 2024). "The LOXL3 staining signal was widely distributed in all layers of the epidermis, in the cells of the dysplastic nevus nests, and in the tumor cells in the basal layer of the epidermis of melanoma in situ samples." (PMID 39273022, 2024). "Furthermore, in a melanoma cell lines study, Loxl3-silenced cells showed a marked decrease in Snai1 compared to the control." (PMID 39273022, 2024). "Although statistical validation of our findings would require analyses of larger sample cohorts, the data from our samples suggest significantly higher LOXL3 fold change gene expression in BRAF+ melanoma than in BRAF– melanoma, dysplastic nevi, and melanoma in situ." (PMID 39273022, 2024).
melanoma (continued). "Importantly, our previous studies unveiled a critical role for LOXL3 in melanomagenesis, and established that melanoma cells are addicted to LOXL3 expression." (PMID 35267510, 2022). "This study builds upon our previous data involving LOXL3 in human melanomagenesis, and offers additional distinct and substantial results that warrant the exploration of LOXL3 as a therapeutic target in malignant melanoma, a very aggressive condition in need of improved treatment options." (PMID 35267510, 2022). "Finally, we confirmed that LOXL3 has a high expression level in both RNA and protein levels, and plays a role in the migration and invasion of melanoma cells." (PMID 36324258, 2022). "Indeed, when we analyzed the expression of these genes in a panel of human melanoma cell lines, the majority of cells carrying activated BRAFV600E mutation expressed LOXL3, SNAIL1, and PRRX1 as determined by gene and protein analyses." (PMID 35267510, 2022). "Complementary in vitro and in vivo studies in primary-derived mouse and established human melanoma cell lines confirmed LOXL3 contribution to melanoma progression, in part by modulating melanoma phenotypic plasticity by regulating the expression of SNAIL1 and PRRX1 EMT-TFs." (PMID 35267510, 2022). "The effects of YTHDF3 and LOXL3 on melanoma were verified in vitro and in vivo." (PMID 36324258, 2022). "The assessment of the metastatic incidence in local and distant lymph nodes from both mice cohorts and the overall quantification of the Tyrp2-stained area indicated a role for Loxl3 in melanoma dissemination, independently of Loxl3 involvement in primary tumor growth." (PMID 35267510, 2022). "What's more, LOXL3 could also regulate the metastasis of melanoma via affecting the expression of MITF, TWIST1, SNAIL1 and PRRX1, which were molecules that involved in EMT process." (PMID 36324258, 2022). "Given the prevalence of BRAF and PTEN alterations in human melanoma, our results, which demonstrated that in vivo targeting of Loxl3 was deleterious to melanomagenesis in a mouse model harboring activated BrafV600E and loss of Pten, warrant future strategies aimed at blocking cellular LOXL3." (PMID 35267510, 2022). "A research also unveiled that LOXL3–SNAIL1–PRRX1 axis was a potent regulatory axis in melanoma." (PMID 36324258, 2022). "Downregulation of LOXL3 inhibits the migration and invasion of melanoma cells and vice versa." (PMID 36324258, 2022). "Indeed, primary melanoma cells showed an upregulation of Mitf and Twist1 and a downregulation of Snai1 and Prrx1 levels upon Loxl3 silencing." (PMID 35267510, 2022). "YTHDF3 and its downstream LOXL3 play a critical role in melanoma metastasis and could serve as a potential therapeutic target to be intervened." (PMID 36324258, 2022). "Importantly, a novel LOXL3-SNAIL1-PRRX1 axis was identified in human melanoma, plausibly relevant to melanoma cellular plasticity." (PMID 35267510, 2022). "The increased expression of LOXL3 was detected in human melanoma and facilitated carcinogenesis." (PMID 33058284, 2020). "In melanoma, LOXL3 is involved in tumorigenesis and tumor progression." (PMID 31340433, 2019). "Finally, we explored potential mechanisms responsible for LOXL3 upregulation in melanoma tumors, in particular epigenetic control." (PMID 29229995, 2018). "Our results reveal an unexpected role for LOXL3 in the control of genome stability and melanoma progression, exposing its potential as a novel therapeutic target in malignant melanoma, a very aggressive condition yet in need for more effective treatment options." (PMID 29229995, 2018). "Besides Hodgkin lymphoma and glioma, LOXL3 highest expression was found in melanoma and chondrosarcoma." (PMID 29229995, 2018).
melanoma (continued). "Interestingly, LOXL2 and LOXL3 were found to be expressed in nearly all the melanoma cell lines studied." (PMID 30701028, 2018). "Notably, BAPN has also been reported to inhibit the activity of other LOX family members, of which LOXL2 and LOXL3 were found to be expressed by both melanoma cells and fibroblasts, making the interpretation of the results complicated." (PMID 30701028, 2018). "Importantly, LOXL3 knockdown was found to be deleterious for cell proliferation in melanoma cells independently of their origin and the oncogenic mutations they harbor." (PMID 29229995, 2018). "Besides, upon LOXL3 silencing, melanoma cells accumulate DSBs and subsequently activate the ATM checkpoint kinase but fail to induce a complete DDR." (PMID 29229995, 2018). "Moreover, upon inhibition of DNA methylation, LOXL3 is upregulated in melanoma cells with minimal endogenous LOXL3 levels." (PMID 29229995, 2018). "Both LOXL3 isoforms were found similarly expressed in most melanoma cells tested." (PMID 29229995, 2018). "Furthermore, the LOXL3-SNAIL1-PRRX1 axis may promote the acquisition of malignant phenotypes in melanoma, affecting tumor cell proliferation and migration capabilities." (PMID 41250755, 2025). "Consequently, LOXL3 has been proposed as a potential therapeutic target for melanoma treatment." (PMID 41250755, 2025). "Hence, we intended to identify the expression and oncogenic role of LOXL3 in melanoma cells." (PMID 36324258, 2022). "Additionally, LOXL3 upregulation in melanoma was correlated with LOXL3 promoter hypomethylation." (PMID 31340433, 2019). "Moreover, LOXL3 is required for efficient DSB repair in melanoma cells." (PMID 29229995, 2018). "Therefore, we hypothesize that LOXL3 allows melanoma cells to survive in the presence of DNA damage since its depletion results in increased DSBs, genomic aberrations and defective mitosis leading to cell death." (PMID 29229995, 2018). "We have found co-expression of LOXL3 and SNAI1 in the perinuclear area of all investigated subgroups, and we have also found NES and SNAI1 co-expression in melanoma cells." (PMID 39273022, 2024). "The major point of our interest was to explore the co-expression of LOXL3, SNAI1, and NES in melanoma development and their supposed role in EMT." (PMID 39273022, 2024). "The survival rates in relation to the high and low mRNA expressions of LOXL3, NES, and SNAI1 in both BRAF-positive (BRAF+) and BRAF-negative (BRAF−) melanoma were analyzed." (PMID 39273022, 2024). "LOXL3, SNAI1, and NES are key factors in melanoma genesis, regulating tumor growth, metastasis, and cellular differentiation." (PMID 39273022, 2024). "Our study, although limited because of the small size of our cohort, provides evidence that the expressions of the investigated markers LOXL3, NES, and SNAI1 change with the progression of melanoma." (PMID 39273022, 2024). "In our study, we explored the potential role of LOXL3, SNAI1, and NES in melanoma progression and metastasis among patients with dysplastic nevi, melanoma in situ, and BRAF+ and BRAF− metastatic melanoma, using immunofluorescence and qPCR analysis." (PMID 39273022, 2024). "We found co-expression of LOXL3 and SNAI1 in the perinuclear area of all investigated subgroups and NES and SNAI1 co-expression in melanoma cells." (PMID 39273022, 2024). "Our results reveal a significant increase in LOXL3 expression and the highest NES expression in BRAF+ melanoma compared to BRAF−, dysplastic nevi, and melanoma in situ." (PMID 39273022, 2024). "Quantitative cell evaluation of LOXL3, NES, and SNAI1 immunoreactivity in dysplastic nevi, melanoma in situ, and BRAF− and BRAF+ melanoma was performed by determining the section percentage area of the epidermal region." (PMID 39273022, 2024).
melanoma (continued). "Our study, using two experimental methods, immunofluorescence and qPCR analysis, reports on the aberrant LOXL3, SNAI1, and NES expression and their co-expression in dysplastic nevi, melanoma in situ, and BRAF+ and BRAF– melanoma." (PMID 39273022, 2024). "The area percentage of LOXL3 was significantly higher in dysplastic nevus compared to BRAF+ (p = 0.0061) and BRAF− melanoma (p = 0.0270)." (PMID 39273022, 2024). "To better understand the role of LOXL3 and its function regulated by YTHDF3, we reversed the expression of LOXL3 in YTHDF3‐ downregulation (shYTHDF3‐1) A375, SK‐MEL‐28 and A2058 melanoma cells." (PMID 36324258, 2022). "LOXL3 is a downstream target of YTHDH3 and re‐expression of LOXL3 reverses its inhibitory effects in migration and invasion of melanoma cells." (PMID 36324258, 2022). "In addition, it will be interesting to explore whether the role of LOXL3 in extracellular matrix remodeling also contributes to the malignant progression of melanoma, which might also impact melanoma cell plasticity, promoting metastasis and the emergence of drug resistance." (PMID 35267510, 2022). "Notably, high LOXL3 and SNAI1 or PRRX1 mRNA levels were significantly associated in human cutaneous melanoma patients, unveiling a previously unknown LOXL3–SNAIL1–PRRX1 axis relevant to melanoma biology." (PMID 35267510, 2022). "It was found that after reversing the expression of LOXL3, the migration and invasion of YTHDF3‐downregulation A375, SK‐MEL‐28 and A2058 melanoma cells were recovered to some extent, which were identified by transwell assay and wound healing experiment." (PMID 36324258, 2022). "Further experiments are needed in order to understand the mechanisms governing the regulation of LOXL3, SNAIL1, and PRRX1 factors in melanomagenesis and their specific contribution to melanoma cell plasticity." (PMID 35267510, 2022). "LOXL3 (lysyl oxidase-like 3) promotes EMT and has a key role in human melanoma cell survival and maintenance of genomic integrity." (PMID 35267510, 2022). "Another study demonstrated that LOXL3 interacted with proteins involved in DNA stability (e.g., BRCA2 and SMC1A) and mitosis completion to accelerate the proliferation of melanoma cells." (PMID 34307505, 2021). "Our results support that the presence of LOXL3 is required for proper DDR and mitosis in melanoma cells." (PMID 29229995, 2018). "Similarly, LOXL3 transduction in a metastatic melanoma cell line (501MEL) harboring minimal endogenous LOXL3 levels promoted migration and invasion without affecting cell proliferation, whereas endogenous LOXL3 silencing had analogous effects as previously shown for other melanoma cell lines." (PMID 29229995, 2018). "In HeLa cells (human cervical cancer cells), melanoma cells, and Madin-Darby canine kidney (MDCK) cells (an epithelial cell model), immunofluorescence staining and western blot analysis revealed that LOXL3 protein is primarily localized in the cytoplasm, with significant perinuclear enrichment." (PMID 41250755, 2025). "Our study demonstrated a substantial increase in the expression of the LOXL3 in BRAF−positive melanoma compared to BRAF−negative melanoma, dysplastic nevi, and melanoma in situ." (PMID 39273022, 2024). "Since we were not able to derive any Loxl3 KO cell line, we reasoned that Loxl3 is necessary for melanoma cell survival in 2D growth conditions, as we have previously shown for human melanoma cells." (PMID 35267510, 2022). "What is more, by MeRIP‐qPCR, we also observed that the m6A level of LOXL3 was not significantly changed between shNC and shYTHDF3 groups in those three melanoma cell lines." (PMID 36324258, 2022). "In addition, we observed a significant correlation between the promoter of invasiveness LOXL3 and expression of NGFR in primary (PT) and metastatic (EM) melanoma." (PMID 36435874, 2022).